HBEGF (heparin binding EGF like growth factor)
Diseases named in the same sentence as HBEGF in open-access papers (continued):
Sharing a sentence is not in itself a finding about the gene and the disease.
glomerulonephritis (7 papers, 2012 to 2024). A renal disorder characterized by damage in the glomeruli. "Investigating toxic changes of biomarkers referred to primary glomerulonephritis revealed a substantial impact of APAP on the heparin-binding growth factor HBEGF at 8 h (Benjamini–Hochberg corrected p = 0.0026, 95% CI = [0.42, 0.96], two-sample t-test)." (PMID 28151932, 2017). "For example, hbEGF involves in kidney diseases such as glomerulonephritis and diabetic kidney disease." (PMID 27881077, 2016). "In addition, HBEGF is expressed in mesangial cells and is involved in mesangial cells proliferation in glomerulonephritis and contributes to lesion formation in focal glomerular sclerosis through stimulation of mitogens at those sites." (PMID 22319602, 2012).
atherosclerosis (6 papers, 2014 to 2025). A disease characterized by the build-up of fatty material and calcium deposition in the arterial wall resulting in partial or complete occlusion of the arterial lumen. "Heparin binding EGF-like growth factor (HB-EGF), which is a member of epidermal growth factor (EGF) family member and a ligand for EGF-receptor (EGFR), is involved in various pathophysiological processes including atherosclerosis and cancer development." (PMID 28792970, 2017).
bladder cancer (6 papers, 2005 to 2020). "Analysis of the bladder carcinoma microarray dataset published by Radvanyi and colleagues showed HBEGF to be overrepresented in infiltrating carcinoma samples." (PMID 23597096, 2013). "In bladder carcinomas, HBEGF transcript levels inversely correlate with patients’ survival times." (PMID 23597096, 2013).
prostate carcinoma (6 papers, 2009 to 2020). A carcinoma that arises from epithelial cells of the prostate gland. "We show that systemic dysregulation of CRGs is also found in prostate cancer, including a 4-gene signature (HBEGF, HOXC13, IGFBP2, and SATB1) capable of differentiating recurrent from non-recurrent prostate cancer." (PMID 27966447, 2017). "HBEGF was unexpectedly downregulated in the recurrent prostate cancer samples, which would appear at odds with its previously documented role in cancer." (PMID 27966447, 2017). "Here we show that a four-gene signature based on HBEGF, HOXC13, IGFBP2, and SATB1 was able to identify patients whose prostate cancer recurred." (PMID 27966447, 2017). "Among those genes, we demonstrated in vitro and in vivo that heparin-binding EGF-like growth factor (HB-EGF) is a new specific biomarker for LPA1 activity in human breast and prostate cancers." (PMID 24828490, 2014).
psoriasis (6 papers, 2009 to 2024). An autoimmune condition characterized by red, well-delineated plaques with silvery scales that are usually on the extensor surfaces and scalp. "EGF receptor (EGFR) ligands, including heparin-binding EGF-like growth factor (HB-EGF), amphiregulin and transforming growth factor (TGF)-α are also TACE substrates and are psoriasis-associated growth factors." (PMID 25384035, 2014). "Multiple EGFR ligands (TGF-α, amphiregulin, heparin-binding EGF-like growth factor) are overexpressed in psoriasis lesions, and transgenic expression of the human amphiregulin gene induces a psoriasis-like phenotype." (PMID 19551138, 2009). "The condition of keratinocytes for the transcription of these two genes, CXCL2 and HBEGF, in keratinocytes may contribute to the necessary and sufficient conditions for triggering inflammatory loops in the epithelial-immune microenvironment (EIME) in psoriasis." (PMID 38312837, 2024).
ischemia (5 papers, 2015 to 2024). A hypoperfusion of the BLOOD through an organ or tissue caused by a PATHOLOGIC CONSTRICTION or obstruction of its BLOOD VESSELS, or an absence of BLOOD CIRCULATION. "Heparin-binding EGF-like growth factor (HBEGF), a hypoxia-inducible neuroprotective protein, was reported to play a neuroprotective role by stimulating the proliferation of neuronal precursor cells during ischemia and reperfusion injury." (PMID 36118760, 2022). "Heparin-binding EGF-like growth factor (HB-EGF), an EGF family member widely distributed in neurons and glia, can be induced by hypoxia and/or ischemia, which contributes to chronic cerebral hypoperfusion (CCH)-mediated Aβ accumulation." (PMID 39594520, 2024).
multiple myeloma (5 papers, 2014 to 2024). "In fact, the heparin-binding EGF-like growth factor (HB-EGF), when released in the tumor microenvironment, induces endothelial cell proliferation in solid cancers and in multiple myeloma." (PMID 35563171, 2022).
Arthritis (4 papers, 2019 to 2025). Inflammation of a joint. "Reference mapping showed that the majority of ICI-arthritis myeloid cells mapped onto four RA myeloid clusters: IL1B + FCN1 + HBEGF+, STAT1+ CXCL10+, SPP1+, and MERTK+ HBEGF+ clusters." (PMID 40662950, 2025).
astrocytoma (4 papers, 2015 to 2026). "The induction of LIF, IL11, and HBEGF mRNA in human astrocytes by FTY-P was confirmed in independent experiments on primary astrocytes and human astrocytoma cells by qPCR." (PMID 26419927, 2015).
endometriosis (4 papers, 2015 to 2025). The growth of functional endometrial tissue in anatomic sites outside the uterine body. "The enrichment of genes such as IL10 and HBEGF in network toxicology analysis suggests that PFAS may contribute to endometriosis by disrupting immune tolerance mechanisms." (PMID 41492385, 2025).
renal fibrosis (4 papers, 2014 to 2024). A final common manifestation of a wide variety of chronic kidney diseases characterized by glomerulosclerosis and tubulointerstitial fibrosis. "In conclusion, our study demonstrates that circRNA_30032 promotes TGF-β1-induced and UUO-induced renal fibrosis via miR-96-5p/HBEGF /KRAS axis and p38MAPK signaling pathway." (PMID 33973871, 2021). "Moreover, knockdown of circRNA_30032 attenuated UUO-induced renal fibrosis by regulating the miR-96-5p/ HBEGF/KRAS axis." (PMID 33973871, 2021). "Moreover, circRNA_30032 silencing suppressed UUO-induced renal fibrosis via the miR-96-5p/HBEGF /KRAS axis." (PMID 33973871, 2021). "CircRNA_30032 silencing significantly reduced renal fibrosis in UUO model mice by increasing miR-96-5p levels and decreasing levels of HBEGF and KRAS." (PMID 33973871, 2021).
brain tumor (3 papers, 2021 to 2026). "In brain tumor patients, HBEGF upregulation is consistently associated with shorter survival (TCGA and CGGA data, N = 1000)." (PMID 41181988, 2026). "Moreover, aggressive cancers including leukemia and pancreatic adenocarcinomas exhibit significant upregulation of HBEGF, warranting further investigations to assess HP‐NP clinical relevance beyond brain tumors." (PMID 41181988, 2026).
meningioma (3 papers, 2019 to 2026). A generally slow growing tumor attached to the dura mater. "CONCLUSION: Cellular senescence-associated genes GAPDH, CCND1, and HBEGF show associations with M2 macrophage polarization and inflammatory cytokine secretion in meningioma." (PMID 41840566, 2026). "Finally, in vitro gene knockdown experiments were performed to validate the functional roles of GAPDH, CCND1, and HBEGF in meningioma and M2 macrophage polarization." (PMID 41840566, 2026). "The expression level of HBEGF in meningioma was lessthan the GBM samples, but the differences were not significant." (PMID 34455717, 2021).
sarcoidosis (3 papers, 2020 to 2024). Sarcoidosis is a multisystemic disorder of unknown cause characterized by the formation of immune granulomas in involved organs. "HBEGF interacts with SOCS3, a suppressor of cytokine signaling with an ability to inhibit Jak/STAT signaling, with elevated expression in lymph nodes sarcoidosis, we previously identified dysregulated HBEGF gene expression in PBMCs sarcoidosis." (PMID 36388923, 2022). "Elevated expression of NAMPT, HBEGF, and ANG-2 was noted in lung and lymph node tissues from individuals with sarcoidosis." (PMID 38611622, 2024). "Quantification of biomarker tissue expression by IHC was largely concordant with plasma biomarker results, with elevated expression of NAMPT, HBEGF, and ANG-2 in lung and lymph node tissues from subjects with sarcoidosis." (PMID 36388923, 2022). "Genomic studies corroborated HBEGF and NAMPT among the top dysregulated genes and identified cytokine-related and fibrotic pathways in lung granulomatous tissues from sarcoidosis." (PMID 36388923, 2022). "This study corroborates previous genomic markers suggested for sarcoidosis such as STAB1, HBEGF, FABP4 and NOTCH4, with HBEGF and NOTCH4 only expressed in lung granulomas." (PMID 33276795, 2020). "These complementary biochemical and genomic approaches indicate that HBEGF, eNAMPT, and ANG-2 may serve as potentially novel indicators of the clinical severity of sarcoidosis." (PMID 36388923, 2022). "In contrast, HBEGF, a heparin-binding epidermal growth factor, was down-regulated in sarcoidosis lung granulomas (FC − 2.36, p = 0.0016) and was not dysregulated in CM or TB." (PMID 33276795, 2020).
squamous cell carcinoma (3 papers, 2013 to 2024). A carcinoma arising from squamous epithelial cells. "Compared with adenocarcinoma, squamous cell carcinoma showed strong communications with endothelial by the MIF/TNFRSF10D, EGFR/GRN, EGFR/HBEGF, and EPHB2/EFNB2 interactions." (PMID 34185421, 2021).
triple-negative breast carcinoma (3 papers, 2018 to 2020). An invasive breast carcinoma which is negative for expression of estrogen receptor (ER), progesterone receptor (PR), and human epidermal growth factor receptor 2 (HER2). "We found that high expression of BHLHE40 or HBEGF is significantly associated with shorter interval of relapse-free survival (RFS) among patients diagnosed with triple-negative breast cancer (TNBC; n = 255) and patients treated with chemotherapy (n = 602)." (PMID 30285805, 2018). "Public databases provided evidence linking high expression of BHLHE40 and HBEGF to poor prognosis of triple-negative breast cancer." (PMID 30285805, 2018).
colon adenocarcinoma (2 papers, 2019 to 2024). "Likewise, human colon adenocarcinoma cell line, HCA-7, has also been reported to release EVs containing EGFR ligands-heparin-binding EGF-like growth factor (HB-EGF) and amphiregulin, that can lead to enhanced invasiveness in tumor cells." (PMID 31146452, 2019).
dementia (2 papers, 2021 to 2025). Loss of intellectual abilities interfering with an individual's social and occupational functions. "The SNPs rs876461 (PRKD3; P = .02), rs117618017 (APH1B; P = .03), rs4844610 (CR1; P = .04), rs7584040 (BIN1; P = 2 × 10–3), rs11168036 (HBEGF; P = 8 × 10–3), rs143429938 (CLU/MIR6843; P = .04), and rs8064326 (KCTD2; P = 3 × 10‐4) were independently associated with incident dementia." (PMID 33532541, 2021).
head and neck squamous cell carcinoma (2 papers, 2011 to 2023). A squamous cell carcinoma that arises from any of the following anatomic sites: lip and oral cavity, nasal cavity, paranasal sinuses, pharynx, larynx, and salivary glands. "In addition, increased expression of HB-EGF (heparin-binding EGF-like growth factor) due to down-regulation of miR-212 in head and neck squamous cell carcinoma (HNSCC) has been described as a possible mechanism of cetuximab resistance." (PMID 22110741, 2011).
heart failure (2 papers, 2019 to 2024). Inability of the heart to pump blood at an adequate rate to meet tissue metabolic requirements. "We found that the expression of both HBEGF and AREG was significantly higher in circulating monocytes of heart failure patients carrying DNMT3A CHIP-driver mutations compared to No-CHIP carriers." (PMID 38242884, 2024).
medulloblastoma (2 papers, 2020 to 2023). A malignant, invasive embryonal neoplasm arising from the cerebellum. "Next, we moved our attention to genes already related to medulloblastoma based on the literature and validated some of them, such as POSTN, BOC, VCAM1, and TP63 among the downregulated genes and ANKRD1, THBS1, NRG1, PTHLH, and HBEGF among the upregulated ones in DAOY and D283Med cells." (PMID 32316671, 2020).
metastatic tumors (2 papers, 2020 to 2021). "Moreover, ADAM22 expression correlated with known brain metastatic associated in both primary (MOCS1, n = 21, p < 0.05) and metastatic tumours (MOCS1, COL13A1, TLR4, HBEGF and PELI2, n = 21, p < 0.05)." (PMID 33208158, 2020).
myxoid liposarcoma (2 papers, 2023). A liposarcoma characterized by the presence of round non-lipogenic primitive mesenchymal cells and small signet ring lipoblasts within a myxoid stoma with a branching vascular pattern. "Furthermore, higher levels of CD68+ TAMs were associated with a poorer OS in myxoid liposarcoma that promoted invasiveness through the heparin-binding EGF-like growth factor (HB-EGF)-EGFR-PI3K/Akt pathway." (PMID 37958467, 2023). "In myxoid liposarcomas, total TAM counts correlate with poor outcomes, as high levels of the TAM-produced heparin-binding EGF-like growth factor (HB-EGF) activate the EGFR-PI3K/Akt pathway in tumor cells, thereby increasing cellular plasticity and promoting chemoresistance." (PMID 38136307, 2023).
necrotizing enterocolitis (2 papers, 2020 to 2022). Necrotizing enterocolitis (NEC) is a devastating disease that affects mostly the intestine of premature infants. "Recent literature has connected decreased HBEGF expression with histological chorioamnionitis, a hallmark of placental inflammation, while increased levels of HBEGF have been proposed to protect the intestinal epithelium in models of necrotizing enterocolitis, a disease attributed to prematurity." (PMID 35471950, 2022).
Nephropathy (2 papers, 2013 to 2014). A nonspecific term referring to disease or damage of the kidneys. "Thus, miR-1207-5p seems to have a protective role in CFHR5 nephropathy when, in the presence of the 1936C allele, is able to bind to the 3′UTR of HBEGF and down-regulate its expression." (PMID 24204837, 2013). "However, the exact mechanism by which HBEGF can alter disease phenotype in CFHR5 nephropathy is currently unknown." (PMID 24204837, 2013).
osteoarthritis (2 papers, 2019 to 2023). A noninflammatory degenerative joint disease occurring chiefly in older persons, characterized by degeneration of the articular cartilage, hypertrophy of bone at the margins and changes in the synovial membrane. "The present study was developed to explore whether microRNA (miR)-760 targets heparin-binding EGF-like growth factor (HBEGF) to control cartilage extracellular matrix degradation in osteoarthritis." (PMID 36894989, 2023).
otitis media (2 papers, 2014 to 2020). Inflammation of the anatomical structures of the middle ear, which is most often caused by an infectious process. "In one study, a link was made between heparin-binding EGF-like growth factor (HB-EGF) and the mucosal epithelial hyperplasia that is commonly observed during otitis media." (PMID 32302357, 2020).
preeclampsia (2 papers, 2014 to 2022). Preeclampsia is a hypertensive disorder of pregnancy that is characterized by new-onset hypertension with proteinuria presenting after 20 weeks of gestation, and depending on mild or severe forms may initially present with severe headache, visual disturbances, and hyperreflexia. "The effect of EGF signaling in preeclampsia is exemplified by HB-EGF (heparin binding EGF like growth factor)." (PMID 25392996, 2014).
arteriosclerosis (1 paper, 2025). A vascular disorder characterized by thickening and hardening of the walls of the arteries. "Heparin-binding epidermal growth factor (HBEGF), a member of the EGF family, plays a role in tissue growth, differentiation, blastocyst implantation, wound healing, smooth muscle cell proliferation, arteriosclerosis, and tumor growth." (PMID 40956822, 2025).
atopic dermatitis (1 paper, 2021). "In addition, the heparin-binding EGF-like growth factor (HB-EGF) released from keratinocytes in atopic dermatitis also increases HAS3 expression." (PMID 34831319, 2021).
depression (1 paper, 2021). "Furthermore, dysregulation of HBEGF has been implicated in depression, and mice in which HBEGF have been knocked out display behavioral phenotypes, which are responsive to antipsychotics as well as altered dopamine and serotonin levels in the brain." (PMID 34420030, 2021).
dysplasia (1 paper, 2018). A usually neoplastic transformation of the cell, associated with altered architectural tissue patterns. "Transgenic mice with intestinal expression of the EGFR ligand heparin-binding EGF-like growth factor (HB-EGF) in the intestine develop colonic serrated polyps, but no dysplasia." (PMID 30323897, 2018).
hypothyroidism (1 paper, 2025). Abnormally low levels of thyroid hormone. "EGFR-dependent autophagy mechanism and the heparin-binding EGF-like growth factor (HB-EGF) are crucial for the loss of neurons and functional impairment in the cerebellum during developing hypothyroidism." (PMID 40237055, 2025).
leukoplakia (1 paper, 2014). A white patch or plaque on a mucous membrane that cannot be characterized clinically or pathologically as any other disease. "Amplified genes mapping within recurrent CNAs (KHDRBS1, PARP1, RAB1A, HBEGF, PAIP2, BTBD7) were selected for validation, by quantitative real-time PCR, in an independent set of 32 progressive leukoplakia, 32 OSSCs and 21 non-progressive leukoplakia samples." (PMID 24403051, 2014).
malaria (1 paper, 2023). Malaria is a serious and sometimes fatal disease caused by a parasite that commonly infects a certain type of mosquito which feeds on humans. "Additional ensemble feature selection revealed CD106, Osteopontin, CD81, major histocompatibility complex class II DR (HLA-DR), and heparin binding EGF like growth factor (HBEGF) together with thrombocytes to be a feature panel for discrimination between healthy and malaria." (PMID 36961624, 2023).
memory impairment (1 paper, 2021). "Finally, three HGS genes, VLDR, FGFR2, and HBEGF, that are involved in synaptic plasticity and memory formation and belong to the red module—which is correlated with E-onset and memory impairment-showed significantly decreased expression in early disease onset patients." (PMID 33986407, 2021).
type A thymoma (1 paper, 2020). "The upstream regulator analysis showed these differential proteins with their overexpression in type A thymoma were likely regulated by HBEGF, LEF1, and GLIPR1." (PMID 31967407, 2020).
ZIKV infection (1 paper, 2018). "Genes associated with cell differentiation and proliferation, such as BUB1, DLGAP5, PBK and CEP55 (Cluster 3) were upregulated during DENV infection but not ZIKV, while EGR1, HBEGF and MAFB (Cluster 4), were up-regulated at d17 POS during ZIKV infection." (PMID 30596671, 2018).